RILP (Rab interacting lysosomal protein)
Description:
Rab effector playing a role in late endocytic transport to degradative compartments. Involved in the regulation of lysosomal morphology and distribution. Induces recruitment of dynein-dynactin motor complexes to Rab7A-containing late endosome and lysosome compartments. Promotes centripetal migration of phagosomes and the fusion of phagosomes with the late endosomes and lysosomes.
Synonyms: PP10141; FLJ31193
Tractability: Small molecule: a structure with a bound ligand is known. PROTAC: its protein half-life has been measured.
Gene: Protein-coding gene on chromosome 17 (1,646,143 to 1,650,077, reverse strand). Ensembl gene ENSG00000167705.
Subcellular location: Late endosome membrane; Lysosome membrane; Cytoplasmic vesicle, phagosome membrane
Pathways (Reactome):
Immune System: MHC class II antigen presentation
Gene Ontology:
Molecular function: dynein light intermediate chain binding; protein binding; small GTPase binding; sterol sensor activity; protein dimerization activity
Biological process: cholesterol homeostasis; early endosome to late endosome transport; endosome to lysosome transport; endosome transport via multivesicular body sorting pathway; intralumenal vesicle formation; lysosome to ER cholesterol transport; negative regulation of protein catabolic process; positive regulation of protein catabolic process; cilium assembly; protein transport
Cellular component: endosome membrane; late endosome; late endosome membrane; lysosomal membrane; lysosome; protein-containing complex; ciliary basal body; cytoplasm; phagocytic vesicle membrane
Genetic constraint (gnomAD): Loss-of-function variants: 53 observed, 28.44 expected, observed/expected ratio (o/e) 1.86, 90% interval 1.45 to 1.98. The synonymous counts are far from expectation, so gnomAD's model fits this gene poorly and the ratio says little. Missense variants: 624 observed, 469.68 expected, observed/expected ratio (o/e) 1.33, 90% interval 1.24 to 1.42. Synonymous variants: 272 observed, 201.62 expected, observed/expected ratio (o/e) 1.35, 90% interval 1.22 to 1.49.
Homologues: Orthologues: chimpanzee RILP (99% identical), dog RILP (74% identical), rabbit RILP (71% identical), pig RILP (70% identical), mouse Rilp (69% identical), rat Rilp (67% identical), guinea pig RILP (65% identical), tropical clawed frog rilp (34% identical), zebrafish rilp (30% identical), Caenorhabditis elegans rilp-1 (21% identical), Drosophila melanogaster Rilpl (21% identical). Paralogues in human: RILPL1 (25% identical), DZIP1L (15% identical), DZIP1 (13% identical), RILPL2 (13% identical).
Diseases named in the same sentence as RILP in open-access papers:
RILP is named in the same sentence as 26 diseases in open-access papers, as found by Europe PMC text mining. Sharing a sentence is not in itself a finding about the gene and the disease. The quoted sentences say what the papers report.
breast carcinoma (3 papers, 2015 to 2023). "Although RILP has been reported to regulate biological processes in many tumors, such as prostate cancer, breast cancer, and hepatocellular carcinoma, its role in osteosarcoma has not been clarified until now." (PMID 37789274, 2023). "In this study, we found that RILP suppresses the proliferation, migration and invasion of breast cancer cells." (PMID 26469971, 2015). "In this study, we showed that overexpression of RILP in breast cancer cells inhibits the migration and invasion, whereas the depletion of RILP by RNAi-mediated knockdown promotes the migration and invasion." (PMID 26469971, 2015). "Our data suggest that RILP suppresses the invasion of breast cancer cells by interacting with RalGDS to inhibit its GEF activity for RalA." (PMID 26469971, 2015). "Our results suggest that RILP suppresses the invasion of breast cancer cells by modulating the activity of RalA through interaction with RalGDS." (PMID 26469971, 2015). "Taken together, RILP may inhibit the invasion of breast cancer cells by modulating the activity of RalA through the interaction with RalGDS to negatively regulate the GEF function." (PMID 26469971, 2015). "As RalGDS functions as Ras-dependent GEF for Ral small GTPases, and is an important regulator in cancer behavior, the interaction of RILP with RalGDS is probably the mechanism (or part of the mechanism) for RILP regulating the proliferation, migration and invasion of breast cancer cells." (PMID 26469971, 2015). "It is demonstrated that overexpression of RILP significantly inhibits the phosphorylation of ERK, whereas shRNA-mediated knockdown of RILP enhanced the phosphorylation of ERK, suggesting that RILP negatively regulates ERK signaling pathway in breast cancer." (PMID 26469971, 2015). "Altogether, these data indicate that the complex V1G1/RILP/RAB7 is crucial for the regulation of cell motility in vitro in breast cancer cells, suggesting that downregulation of these three factors is required for cancer progression and, in particular, for cell migration in breast cancer." (PMID 33633298, 2021).
prostate carcinoma (2 papers, 2015 to 2023). A carcinoma that arises from epithelial cells of the prostate gland. "RILP (Rab7-interacting lysosomal protein) is a key regulator for late endosomal/lysosomal trafficking, and probably a tumor suppressor in prostate cancer." (PMID 26469971, 2015).
atherosclerosis (1 paper, 2020). A disease characterized by the build-up of fatty material and calcium deposition in the arterial wall resulting in partial or complete occlusion of the arterial lumen. "Based on the results of our present study, RILP might be a new target for the pathogenesis of atherosclerosis." (PMID 32616722, 2020). "However the mechanisms of RILP on atherosclerosis are still unknown." (PMID 32616722, 2020).
choroideremia (1 paper, 2023). Choroideremia (CHM) is an X-linked chorioretinal dystrophy characterized by progressive degeneration of the choroid, retinal pigment epithelium (RPE) and retina. "Physiological interactors of Rab 7 are RILP, OSBP and the Rab escort protein 1 or CHM choroideremia protein, which is the substrate-binding subunit of the Rab geranylgeranyltransferase complex." (PMID 37243184, 2023).
invasive breast carcinoma (1 paper, 2015). A carcinoma that infiltrates the breast parenchyma. "The downregulation of RILP in invasive breast cancer cells is consistent with this possibility." (PMID 26469971, 2015).
kidney cancer (1 paper, 2016). Primary or metastatic malignant neoplasm involving the kidney. "Taken together, these data are strongly supportive of a DENN domain‐dependent role for FLCN regulation of lysosome distribution through a Rab34/RILP axis in BHD kidney cancer cells." (PMID 27113757, 2016).
lentivirus infection (1 paper, 2023). Virus diseases caused by the Lentivirus genus. "Later, we also silenced RILP in osteosarcoma cells through lentivirus infection." (PMID 37789274, 2023).
liver inflammatory diseases (1 paper, 2023). "We previously linked inflammasome activation to both increased RILP cleavage and increased EV secretion in several liver inflammatory diseases, including progressive NALFD." (PMID 37051862, 2023). "Because cell–cell crosstalk is an important driver in the progression of several disease states, we wanted to assess the role of RILP cleavage in the promotion of inflammatory liver disease using a mouse model." (PMID 37051862, 2023). "Because RILP cleavage influences both the abundance of EV secretion as well as cargo specificity, we hypothesized that RILP cleavage significantly contributes to the promotion and progression of inflammatory liver disease." (PMID 37051862, 2023).
Obesity (1 paper, 2021). Accumulation of substantial excess body fat. "RILP and FNIP2 were associated to a SI score > 20 and PLIN2 was associated with obesity in the two families." (PMID 33807278, 2021).
osteosarcoma (1 paper, 2023). A usually aggressive malignant bone-forming mesenchymal neoplasm, predominantly affecting adolescents and young adults. "A higher expression of RILP is associated with lower malignancy and more favorable outcomes in osteosarcoma patients." (PMID 37789274, 2023). "740Y-P, a highly selective activator of PI3K, was found to attenuate the inhibitory effect on osteosarcoma cell proliferation, migration, and invasion caused by RILP overexpression." (PMID 37789274, 2023). "Our study revealed that the expression of RILP was associated with favorable prognosis of osteosarcoma and RILP inhibits proliferation, migration, and invasion and promotes autophagy in osteosarcoma cells via Grb10-mediated inhibition of the PI3K/AKT/mTOR signaling pathway." (PMID 37789274, 2023). "In the wound healing and transwell invasion assays, 3-MA treatment attenuated the inhibitory effect of RILP on the metastasis ability of osteosarcoma cells." (PMID 37789274, 2023). "Functionally, RILP inhibits proliferation, migration, invasion, and promotes autophagy in osteosarcoma cells via Grb10-mediated inhibition of the PI3K/AKT/mTOR signaling pathway." (PMID 37789274, 2023). "Functional experiments suggested that downregulation of Grb10 attenuated the inhibition effect of RILP on osteosarcoma cell proliferation, migration, and invasion, the opposite is true for Grb10 overexpression." (PMID 37789274, 2023). "Using RNA-seq data analysis, we uncovered the mechanism of action of RILP in osteosarcoma, at least in part, through its regulation of the PI3K/AKT/mTOR pathway, which in turn regulated the proliferation, migration, and invasion of osteosarcoma cells." (PMID 37789274, 2023). "Subsequently, the cells were treated with 740Y-P, a highly selective activator of PI3K, and partial reversal of the inhibitory effects of RILP on the proliferation, migration, and invasion of osteosarcoma cells, were observed." (PMID 37789274, 2023). "Overexpression of RILP significantly inhibited proliferation and impaired metastasis ability of osteosarcoma cells, while silencing of RILP showed the opposite trend." (PMID 37789274, 2023). "CCK-8, colony formation, and Ki-67 staining assays showed that knockdown of RILP significantly enhanced the OD450 value, colony cells, and Ki-67-positive cells, suggesting that RILP downregulation accelerates the proliferation of osteosarcoma cells." (PMID 37789274, 2023). "Conversely, silencing of RILP promoted the malignancy of osteosarcoma cells, further demonstrating the tumor suppressor function of RILP." (PMID 37789274, 2023). "Subsequently, wound healing assays suggested that stable overexpression of RILP significantly impaired migration of osteosarcoma cells." (PMID 37789274, 2023). "Wound healing and transwell assays revealed enhanced migration and invasion abilities in RILP knockout osteosarcoma cell lines." (PMID 37789274, 2023). "We subcutaneously injected stably overexpressing 143B osteosarcoma cells into nude mice and observed that overexpression of RILP inhibited tumor growth by inhibiting the PI3K/AKT/mTOR pathway." (PMID 37789274, 2023). "Clinically, osteosarcoma patients with higher expression levels of RILP have a better outcome than those with lower expression levels." (PMID 37789274, 2023). "Our work presents a novel therapeutic approach for the treatment of osteosarcoma and highlights the vital role of RILP as a therapeutic target in osteosarcoma treatment." (PMID 37789274, 2023). "Rab-interacting lysosomal protein (RILP) contains an alpha-helical coil with an unexplored biological function in osteosarcoma." (PMID 37789274, 2023). "The protein and mRNA expression of RILP in osteosarcoma specimens was lower than those in adjacent normal tissues." (PMID 37789274, 2023). "Compared with LV-Control, the tumors induced by RILP-overexpressing 143B osteosarcoma cells were much smaller, suggesting that RILP upregulation reduced tumor size in vivo." (PMID 37789274, 2023).
osteosarcoma (continued). "Western blot analysis showed increased protein expression levels of N-cadherin and Vimentin and a decreased level of E-cadherin; thus suggesting that the downregulation of RILP significantly promotes the metastatic ability of osteosarcoma cells." (PMID 37789274, 2023). "This study investigated the expression of RILP in osteosarcoma cells and tissues to determine the effect of RILP on the biological behaviors of osteosarcoma cells and the underlying mechanism." (PMID 37789274, 2023). "Overall, our research revealed that the effect of RILP on EMT in osteosarcoma cells was partly mediated through autophagy." (PMID 37789274, 2023). "In this study, we investigated the unique role of RILP on proliferation, migration, invasion and autophagy of osteosarcoma using osteosarcoma cell lines and animal models." (PMID 37789274, 2023). "In conclude, RILP restrains osteosarcoma progression via Grb10-mediated inhibition of the PI3K/AKT/mTOR pathway." (PMID 37789274, 2023). "Similarly, transwell assay revealed that RILP overexpression attenuated invasion of osteosarcoma cells." (PMID 37789274, 2023). "We suspected that whether hypermethylation of promoter sites leads to a reduction of RILP expression in osteosarcoma." (PMID 37789274, 2023). "In this study, we observed that RILP could interact with Grb10 and promote its phosphorylation, thus affecting the malignant phenotypes of osteosarcoma." (PMID 37789274, 2023). "In addition, the protein and mRNA expression levels of RILP at the cellular level revealed that osteosarcoma cells expressed lower level of RILP than that in hFOB1.19 cells, especially in 143B and U2OS cells." (PMID 37789274, 2023). "We then measured the expression level of RILP in human osteosarcoma and normal tissue specimens." (PMID 37789274, 2023). "Our study demonstrated the role of RILP as a tumor suppressor gene in osteosarcoma." (PMID 37789274, 2023). "Finally, Kaplan-Meier survival analysis was performed using data from the GEO and TCGA databases; the results suggested that lower expression of RILP predicted poorer prognosis in patients with osteosarcoma." (PMID 37789274, 2023). "Co-immunoprecipitation assay in 143B osteosarcoma cells showed that RILP interacted with Grb10." (PMID 37789274, 2023). "Therefore, our results validated that RILP was a tumor suppressor gene and a potential prognostic factor for osteosarcoma." (PMID 37789274, 2023). "Since activation of autophagy can promote or inhibit the EMT process, we hypothesized that the effect of RILP on EMT in osteosarcoma cells is mediated through autophagy." (PMID 37789274, 2023). "Thus, our results suggested that the overexpression of RILP increased the autophagy level of osteosarcoma cells, thereby inhibiting osteosarcoma cell migration and invasion." (PMID 37789274, 2023). "In the future, targeting RILP may be a potential strategy for osteosarcoma treatment." (PMID 37789274, 2023). "Additionally, upregulation of RILP restrained the progression of osteosarcoma cells." (PMID 37789274, 2023). "3-Methyladenine (3-MA), a selective autophagy inhibitor, partially attenuated the inhibitory effect of RILP on the migration and invasion ability of osteosarcoma cells, suggesting the involvement of autophagy in epithelial–mesenchymal transition regulation in osteosarcoma cells." (PMID 37789274, 2023). "We further verified that overexpression of RILP restrained the PI3K/AKT/mTOR signaling pathway and induced autophagy in osteosarcoma cells, while the opposite trend was observed when PI3K pathway activator 740Y-P was used." (PMID 37789274, 2023). "Since Grb10 is involved in negative regulation of the PI3K/AKT signaling pathway, we hypothesized that RILP could interact with Grb10 to inhibit the PI3K signaling pathway, ultimately affecting the osteosarcoma phenotype." (PMID 37789274, 2023).
osteosarcoma (continued). "Our results identified that RILP could bind to Grb10 and participate in the inhibition of the PI3K signaling pathway, thus affecting the progression of osteosarcoma." (PMID 37789274, 2023). "Therefore, combined targeting of RILP and the PI3K/AKT/mTOR signaling pathway may provide a new therapeutic strategy for osteosarcoma." (PMID 37789274, 2023). "However, the drawback of this study is that the specific reasons for RILP downregulation in osteosarcoma were not investigated in detail." (PMID 37789274, 2023).
type 2 diabetic (1 paper, 2024). "In addition, the transcription of RILP is upregulated in high fat-fed type 2 diabetic mice." (PMID 39195203, 2024).
viral infection (1 paper, 2022). "Studies have shown that the RAB7 adaptor protein RILP (RAB-interacting lysosomal protein), which is critical for linking RAB7-positive vesicles to dynein motor complexes, is cleaved after inflammation or viral infection, to form a RILP cleavage fragment (cRILP)." (PMID 35629824, 2022).
cancer (8 papers, 2015 to 2025). A tumor composed of atypical neoplastic, often pleomorphic cells that invade other tissues. "Our results show that the Arg/N-degron pathway modulates exosome-mediated apoptosis in cancer cells under oxidative stress underlying RILP-dependent secretion of ANXA1." (PMID 40520087, 2025). "To uncover the molecular mechanisms underlying the role of RILP in regulating cancer cell properties, we searched for the interacting partners of RILP through yeast-two-hybrid screening using a pretransformed human fetal brain cDNA library." (PMID 26469971, 2015). "However, the role of RILP in other cancers and the underlying mechanism for RILP in regulating the invasion of cancer cells remain to be investigated." (PMID 26469971, 2015). "Using the TIMER database, we found that RILP was significantly differentially expressed in several cancers." (PMID 37789274, 2023). "This further suggests that the PI3K/AKT/mTOR signaling pathway plays a key role in cancer inhibition mediated by RILP." (PMID 37789274, 2023). "A critical remaining question is the identification of an Nt-arginylation-permissive substrate that regulates caspase-1 protein levels via either transcription or degradation, thereby affecting RILP cleavage and its downstream exosome formation in cancer cells." (PMID 40520087, 2025). "On the other hand, the increased candidates included proteins involved in the blockade of cancer cell migration and invasion (SCAI, CARMIL2), autophagy activation (HSBP1, RILP) as well as proteins that can be considered as anti-tumorigenic (SCG2, DIP2A, HSBP1)." (PMID 39833546, 2025). "Together, we hypothesize that RILP interacts with RalGDS, and consequently inhibits its GEF activity, resulting in inhibition of RalA activation, thus suppresses the secretion and cytoskeleton reconstruction required for cell migration and invasion of cancer cells." (PMID 26469971, 2015).
tumor (4 papers, 2015 to 2023). "Conversely, Rab7 and its effector RILP promote retrograde traffic toward the microtubule-organizing center via recruitment of dynein motors and we recently identified Rab7 as a potential tumor suppressor through its control of lysosome positioning." (PMID 27105540, 2016). "Using a large independent database and human tissue samples, we systematically analyzed the differences in the expression of RILP between tumor and normal tissues and confirmed that RILP was significantly decreased in tumor tissues compared with that in normal tissues." (PMID 37789274, 2023).
neurodegenerative disease (1 paper, 2024). A disorder of the central nervous system characterized by gradual and progressive loss of neural tissue and neurologic function. "Inhibition of RILP expression results in impaired integrity of the autophagic flux in neuronal cells, whereas promotion of RILP expression contributes to the treatment of neurodegenerative diseases." (PMID 39958873, 2024).
RILP also shares sentences with these, for which no sentence is quoted: lung carcinoma (3 papers); hepatocellular carcinoma (2); Alzheimer disease (1); cardiovascular disease (1); diabetes mellitus (1); immune deficiency (1); infection (1); Intellectual disability (1); ischemic stroke (1); Miller-Dieker syndrome (1); ovarian carcinoma (1).